FOXM1 (forkhead box M1)
Diseases named in the same sentence as FOXM1 in open-access papers (continued):
Sharing a sentence is not in itself a finding about the gene and the disease.
tumor (continued). "Our data demonstrate a role of the AKT1/SIRT1/FOXM1 axis in the expression of the tumor suppressor ERβ." (PMID 26885609, 2016). "MELK is thought to bind and activate transcription factors c-JUN and FOXM1 and play a role in maintaining tumor initiating cells." (PMID 27574806, 2016). "Inhibition of its enzymatic regulator Pin1 or the Pin1-FOXM1 interaction successfully repressed FOXM1 activity and tumor proliferation ex vivo of in a freshly cultured human melanoma tumor and in 3D-cultured patient-derived melanoids." (PMID 26279295, 2016). "For example in endothelial cells FOXM1 has an unanticipated tumor suppressive function as it limits canonical Wnt signaling in lung epithelial cells." (PMID 27074562, 2016). "Strikingly, the acetylation mutant of FOXM1 (FOXM1-5KR) significantly reduced tumor growth in nude mice, indicating that FOXM1 acetylation plays an important role in tumor growth." (PMID 27542221, 2016). "Western blot and qRT-PCR analyses showed that the expression of GLUT1 and HK2 was decreased by FOXM1 knockdown, which was further confirmed by immunohistochemical examination of xenograft tumor sections." (PMID 27351131, 2016). "The results indicate persistence of RT-induced DNA-damage lesions after FOXM1 inhibition in GBM tumor stem cells, whereas the majority of DNA lesions were repaired in normal astrocytes." (PMID 27764801, 2016). "Several studies suggest that mono- or combination therapies targeting FoxM1 can have potent anti-tumor effects." (PMID 27259271, 2016). "Both OTUB1 and FOXM1 were highly expressed in tumor lesions relative to paratumorous tissues with statistically significant correlation (r=0.610, p<0.01)." (PMID 27167337, 2016). "Overexpression of FoxM1 in various tumors indicates a strong dependence of the tumor cells on FoxM1 expression because of an integral role of FoxM1 in tumorigenesis." (PMID 27351282, 2016). "Our previous study has shown that P27KIP1, one of the important inhibitors of cell cycle and a tumor suppressor, is the down-stream target of FoxM1 and regulated by FoxM1 activity." (PMID 27086911, 2016). "Compared to the untreated controls, decreased FOXM1 expressions were recognized in treated tumor cells by Western blotting." (PMID 27439614, 2016). "Immunohistochemical study of 106 tumor specimens was conducted to evaluate their immunohistochemical expression of FOXM1." (PMID 27439614, 2016). "A multivariate Cox proportional hazards model showed that histologic grade, vascular invasion, Gli2, FoxM1 and KIF20A were significantly associated with tumor recurrence and overall patient survival." (PMID 27036048, 2016). "In contrast, the combination of FOXM1 knockdown and gefitinib led to marked inhibition of the tumor growth compared with either FOXM1 knockdown or gefitinib monotherapy." (PMID 27494877, 2016). "Here, we identified miR-671-5p as a tumor-suppressor miRNA by targeting Forkhead Box M1 (FOXM1), an oncogenic transcription factor, in breast tumorigenesis." (PMID 26588055, 2016). "We observed decreased expression levels of genes associated with DNA repair (MRE11, RAD51) and genes involved in cell cycle and chromosomal segregation (PLK1) after FOXM1 inhibition in both GBM tumor cells and stem cells." (PMID 27764801, 2016). "Immunoblot analysis confirmed the increased levels of FOXM1 in irradiated GBM tumor cells (U251 and U87)." (PMID 27764801, 2016). "This deference effect of FOXM1 interruption between the two cell lines, suggested that the FOXM1 involved in SS tumor progression in a variety of ways." (PMID 27439614, 2016). "Downregulation of FOXM1 by siRNA was also seen to inhibit GBM tumor cell and stem cell proliferation." (PMID 27764801, 2016). "MMP9 is a known target of FoxM1, a key transcription factor that regulates tumor invasiveness and metastasis." (PMID 27259271, 2016). "Since we found that there was significant correlation between the FOXM1 expression and tumor thickness (p = 0.046)." (PMID 26640950, 2015).
tumor (continued). "It has shown that FOXM1 promoted tumor metastasis by regulating epithelial-mesenchymal conversion (EMT) in tumor cells." (PMID 26451068, 2015). "In contrast to the previous report, FoxM1 inhibition by shRNA-mediated knockdown provided rather subtle survival gain in tumor bearing mice in our study." (PMID 26444992, 2015). "Expression of FoxM1 is dramatically elevated in tumor cells derived from liver, lung, colon, breast and prostate." (PMID 26264222, 2015). "Compared to the untreated control cells, surviving tumor cells after irradiation revealed high expression of both FoxM1 and Sox2." (PMID 26444992, 2015). "TS when administrated intraperitoneal at 50 mg/kg to mice harboring human MM tumor xenografts significantly decreased nuclear FOXM1 expression and tumor volume compared to vehicle and 5 mg/kg TS treated animals." (PMID 26011724, 2015). "Induction of FoxM1 leads to promotion of tumor cells proliferation by diminishing nuclear levels of p21 protein and increasing cyclin B1 and cyclin D1 expression." (PMID 25973397, 2015). "While all mice formed tumors, FOXM1 KD significantly reduced the tumor and ascites load in the mice." (PMID 26299613, 2015). "Beyond that cell proliferation, FOXM1 also plays important roles in tumor angiogenesis, EMT, invasion, and metastasis." (PMID 25935853, 2015). "The tumor nodule numbers and sizes, and the tumors grew on the ovaries in particular, as well as ascites volumes were significantly reduced in FOXM1-KD cell injected mice, compared to control mice." (PMID 26299613, 2015). "MiR-494 has also been demonstrated to attenuates tumor growth and metastasis in vitro and in vivo by targeting FOXM1." (PMID 26090866, 2015). "To evaluate functional significance of FoxM1 in radiation resistance of GBM, we inhibited FoxM1 by shRNA-mediated knockdown and assessed its effects on tumor cell survival and growth." (PMID 26444992, 2015). "In summary, FOXM1 was involved in tumor proliferation, invasion, metastasis, and angiogenesis by regulating the expression of downstream genes related to the tumor and thereby affected the prognosis of patients." (PMID 26451068, 2015). "Experimental factors such as FoxM1 knockdown efficacy, the usage of different tumor cells, and the number of injected tumor cells are likely reasons of this discrepancy." (PMID 26444992, 2015). "The transcript levels of POH1 and its downstream genes Survivin and FOXM1 in the tumour tissues were aberrantly upregulated in comparison with those in the non-tumour samples." (PMID 26510456, 2015). "All in all, these results suggested that FOXM1 promoted or facilitated the invasion and metastasis of tumor cells through a variety of pathways." (PMID 26451068, 2015). "Our study demonstrates that the combination of thiostrepton, a FOXM1 inhibitor, and cisplatin significantly decreases the expression of stem cell markers and suppresses tumor formation in vivo." (PMID 25537512, 2015). "On one hand, FoxM1 (a key TF for cell cycle progression and a critical molecule for tumor development and progression) is shown to be induced by hypoxia via direct binding of Hif-1 to its promoter sequence, which causes its up-regulation." (PMID 25973397, 2015). "This study aims to identify new FoxM1 targets in regulating tumor metastasis using bioinformatics tools as well as biological experiments." (PMID 26264222, 2015). "Proliferation defects in SPDEF-containing tumor cells were corrected by re-expression of Foxm1, providing direct evidence that SPDEF inhibits tumor cell proliferation through Foxm1." (PMID 25254494, 2014). "Forkhead box M1 (FoxM1) is described as a major oncogenic transcription factor in tumor initiation, promotion and progression." (PMID 25522167, 2014).
tumor (continued). "Downregulation of OGT in tumor cells leads to increased degradation of the oncogenic transcription factor Forkhead transcription factor (FoxM1) protein, a direct regulator of VEGFR-2 and FoxF1 expression in EC." (PMID 25149532, 2014). "We previously showed that FOXM1 acts downstream of 14-3-3ζ signaling, the elevation of which correlates with a more aggressive tumor phenotype." (PMID 25213081, 2014). "Among the three major isoforms of FOXM1, FOXM1B is highly associated with tumor growth and metastasis." (PMID 24918286, 2014). "We validated the correlation between FOXM1 expression and tumor progression and metastasis by in vitro functional studies." (PMID 24885308, 2014). "Overexpression of FOXM1 in various tumors indicates a strong dependence of the tumor cells on FOXM1." (PMID 24824601, 2014). "We used a polyethylimine-based cationic polymer, JetPEI (Polyplus) as an encapsulation agent for the in vivo delivery agent for FOXM1-siRNA by direct intratumoral injection at a dose of 10 μg siRNA/tumor, 3 times per week." (PMID 25093142, 2014). "It has been reported that a number of FOXM1 downstream target molecules are involved in regulating tumor progression and invasive behaviors." (PMID 24885308, 2014). "Collectively, those findings strongly support the potential role of FOXM1 in TAMs infiltration and recruitment and tumor development and progression." (PMID 24325450, 2013). "FoxM1 was found significantly upregulated in recurrent GBM tumor samples compared with primary tumors, and its expression levels correlated with poor response to the alkylator temolozide." (PMID 23467617, 2013). "In order to explore the influence of different FOXM1 status on other independent prognostic factors, we performed a stage-stratified analysis of tumor size, pT, and pTNM according to FOXM1 expression levels." (PMID 24004449, 2013). "We showed that FoxM1 overexpression was related to reduced overall survival and rapid tumor progression in NSCLC patients." (PMID 23536876, 2013). "Of these, the most informative protein appeared to be transcriptional factor Forkhead Box M1 (FoxM1), a crucial element for cell cycle regulation and an important regulator of tumor metastasis." (PMID 23620736, 2013). "FOXM1 was expressed in numerous tumor cell lines and regulated the expression of genes involved in cell cycle." (PMID 23762558, 2013). "Siomycin A has been shown to decrease FOXM1 expression with resulting apoptotic cell death in several tumor systems." (PMID 23365673, 2013). "Similar to the pattern we observed for Anxa1 expression, we found that FoxM1 mRNA was also up-regulated in tumor cells than the paired adjacent normal brain tissues." (PMID 23991102, 2013). "The wide range of activities in multiple tumor systems makes FOXM1 a potentially inviting target for anticancer therapeutics." (PMID 23365673, 2013). "Consistent with findings in other tumor systems, there is significant reduction in FOXM1 transcript with overnight treatment in the low micromolar range." (PMID 23365673, 2013). "When FoxM1 expression was compared between normal brain regions versus tumor areas of individual mice, tumors had more than 200-fold higher expression than normal brain regions." (PMID 23404835, 2013). "The same research team has further shown that expression of FOXM1 in macrophages is required for pulmonary inflammation, recruitment of macrophages into the tumor site and lung tumor growth." (PMID 24325450, 2013). "Considering the role of FoxM1 in the tumor cell growth, some studies have evaluated the possibility of FoxM1 expression as a biomarker to predict the clinical outcome of NSCLC patients." (PMID 23536876, 2013). "Multiple oncogenic functions have been attributed to FOXM1 in diverse tumor types, including proliferation, tumorigenicity, epithelial to mesenchymal transition, cell migration, and drug resistance." (PMID 23365673, 2013).
tumor (continued). "Using this database, coexpression of MELK in GBM tumor samples was confirmed (p < .0001) with FOXM1 expression." (PMID 23404835, 2013). "Recent studies have shown that FOXM1 promotes macrophage migration and recruitment during inflammation and tumor formation." (PMID 24325450, 2013). "To determine if FOXM1 is a relevant therapeutic target in MM, we examined FOXM1 expression in tissue arrays of human MM tumor specimens with a polyclonal FOXM1 antibody at multiple dilutions (1∶1000, 1∶2000 and 1∶3000), as in another study." (PMID 22761781, 2012). "FoxM1 is ubiquitously expressed in all proliferating cells, including many tumor-derived cell lines." (PMID 23006512, 2012). "TS induces cell cycle arrest and selectively kills breast cancer cells through down-regulation of FOXM1 protein and RNA expression, and acts synergistically with other agents to promote tumor cell apoptosis." (PMID 22761781, 2012). "FoxM1 staining level significantly correlated with primary tumor stage (P < 0.001), lymph node metastasis (P = 0.01), distant metastasis (P = 0.01), TNM stage (P < 0.001) and histological grade (P = 0.003)." (PMID 23006512, 2012). "As for other tumor cell types, TS inhibited expression of FOXM1 in MM cells in a dose-dependent manner." (PMID 22761781, 2012). "We selected the forkhead box M1 (FoxM1) for further study because of its well-characterized role in tumor biology." (PMID 22900969, 2012). "Quantification of FOXM1 mRNA expression in MM tumor specimens and matched control tissues from four individuals showed that FOXM1 mRNA is elevated in human MM, confirming the results obtained by immunohistochemistry." (PMID 22761781, 2012). "Five target genes were significantly overexpressed in the tumour samples compared with normal bladder tissue: FOXM1, IGF2, OSF2, and H19, which promote cell proliferation and growth, and SPP1, which is involved in extracellular matrix interactions." (PMID 22361633, 2012). "Multivariate Cox regression analyses showed that advanced primary tumor stage (P = 0.001), distant metastasis (P = 0.025) and high FoxM1 expression (P = 0.008) were independent prognostic factors." (PMID 23006512, 2012). "In fact, genomic studies have identified FoxM1 to be one of the highest expressed genes in a wide range of human tumors, where a correlation between tumor aggressiveness and FOXM1 expression levels have been shown." (PMID 22203467, 2011). "We found a similar decrease in lung tumorigenesis regardless if Foxm1 was deleted prior to the tumor initiation or during tumor progression." (PMID 19672312, 2009). "Inhibition of Foxm1 in cultured tumor cells with either siRNA transfection or pharmacological agents caused a cell cycle arrest." (PMID 19672312, 2009). "Even with the contribution of non-tumor cell RNA (endothelial cells, macrophages, fibroblasts), the Real-time RT-PCR analysis revealed decreased Foxm1 mRNA levels in epFoxm1−/− tumors compared to control Foxm1fl/fl tumors." (PMID 19672312, 2009). "Altogether, these results indicate that Foxm1 deletion from type II lung epithelial cells is sufficient to reduce proliferation of tumor cells in vivo and decrease urethane-mediated lung tumorigenesis." (PMID 19672312, 2009). "The conditional deletion of Foxm1 from lung epithelial cells strikingly decreased the development of lung tumors in mice, diminished proliferation of tumor cells and reduced the expression of cyclin B1 and TOPO-2α." (PMID 19672312, 2009). "Consistent with its role in proliferation, elevated expression of FOXM1 has been reported in a variety of human tumour entities." (PMID 18254960, 2008). "In accordance with the observed role of FOXM1 in cell cycle progression and cell proliferation, elevated expression of FOXM1 has been reported in several human tumour entities." (PMID 18254960, 2008).
tumor (continued). "However, FOXM1 mutation is only overexpressed in circulating immune cells, which challenges the conventional conclusion that FOXM1 is directly involved in the growth and proliferation of tumor cells." (PMID 41584858, 2026). "Notably, proximal-specific FOXM1 targets were heavily enriched in mitotic spindle and G2/M checkpoint modules, suggesting a proliferative tumor phenotype." (PMID 40862793, 2025). "Similarly, MYBL2 promotes cell cycle progression by transactivating targets, such as CDCA3, and interacting with FOXM1 to potentiate Wnt signaling, thereby further promoting tumor progression." (PMID 41439026, 2025). "TST's regulation of FoxM1 further impacts the biological behavior of tumor cells." (PMID 41036313, 2025). "We also tested FOXM1 expression levels across 15 tumor types using the combination of the two largest human datasets for tumor (TCGA) and normal (GTEx) transcriptome-wide datasets, and detected a strikingly consistent upregulation of FOXM1 in all tumor types." (PMID 39858603, 2025). "Therefore, owing to these limitations, the exploration of unidentified roles for FOXM1 such resistance to FOXM1i and/or mechanistic involvement in the modulation of tumor-immune response will provide further exciting opportunities of study." (PMID 40630538, 2025). "Compared with that in the control group, the expression of lncRNA-PVT1 and FoxM1 was significantly upregulated in the tumor tissues of mice inoculated with Huh7 cells co-cultured with exosomes from hypoxia-induced HepG2 cells (p = 0.018 and p < 0.001, respectively)." (PMID 40486884, 2025). "For example, knocking down FOXM1 or STAT3 in proximal models may reduce tumor growth, while overexpressing CDX2 or GATA6 could induce a more differentiated, less aggressive phenotype, advancing therapeutic understanding and precision medicine." (PMID 40862793, 2025). "Notably, in HIN and LIN, the coefficient correlation of UBE2S, HIF‐1α, and FOXM1 increased as an increase in tumor grade." (PMID 41427004, 2025). "FOXM1, encoding a transcription factor that regulates cell cycle and DNA repair, is markedly upregulated in LIHC and is linked to poor clinical outcomes and increased tumor aggressiveness." (PMID 40251374, 2025). "Similarly, PTTG1 has been shown to influence NF-κB activation through its regulatory effects on FOXM1 expression, linking its activity to tumor progression and immune system modulation." (PMID 40072059, 2025). "Therefore, targeting FOXM1 can prevent tumor progression and growth by suppressing key proteins involved in cell proliferation, invasion, angiogenesis, and tumorigenicity." (PMID 40725039, 2025). "Additionally, FOXM1 regulates the stemness of OC cells and promotes tumor progression by interacting with the WNT/β-catenin signaling pathway." (PMID 40612352, 2025). "Interestingly, it was observed that FOXM1 inhibitors alone or in combination with cisplatin showed synergistic anti-tumor response in naïve and CR-SCLC cell line." (PMID 40630538, 2025). "Forkhead box protein M1 (FOXM1) is an oncogene involved in regulating tumor growth and metastasis." (PMID 38333593, 2024). "Recent findings have indicated that FOXM1-induced autophagy may contribute to chemotherapy resistance in other tumor cells." (PMID 39086352, 2024). "By administrating thiostrepton (TST), which is a protein translation inhibitor that has been reported to inhibit FOXM1 activity 43, we observed that pharmacological inhibition of FOXM1 was sufficient to induce tumor-inhibitory effect and potentiated the response to anti-PD-1 in the LLC mouse model." (PMID 38577601, 2024). "By upregulating SNAIL, an EMT phenotype promoter, FOXM1 drives tumor invasion and metastasis." (PMID 39594778, 2024). "Targeting Foxm1 through SPDEF may be an option to disrupt the positive feedback loop that accelerates tumor cell proliferation." (PMID 38674385, 2024).